PTBP1 (polypyrimidine tract binding protein 1)
Diseases named in the same sentence as PTBP1 in open-access papers (continued):
Sharing a sentence is not in itself a finding about the gene and the disease.
low grade glioma (2 papers, 2023 to 2024). A grade I or grade II glioma arising from the central nervous system. "High PTBP1 expression had a notable impact on the OS of patients with low-grade glioma (LGG)." (PMID 37808305, 2023). "Particularly in low-grade glioma (LGG), PTBP1 shows significant positive correlations with critical tumor characteristics such as neoantigen load, tumor mutation burden, and immune cell infiltration." (PMID 38918441, 2024).
metabolic syndrome (2 papers, 2022 to 2024). A cluster of metabolic risk factors for CARDIOVASCULAR DISEASES and TYPE 2 DIABETES MELLITUS. "For example, overexpressed hsa_circH19 has been demonstrated as an independent risk factor for metabolic syndrome, which may sequester polypyrimidine tract-binding protein 1 (PTBP1), resulting in the inhibition of sterol-regulatory element-binding proteins (SREBP1s) precursor cleavage." (PMID 34908111, 2022).
nasopharyngeal carcinoma (2 papers, 2017 to 2021). A carcinoma arising from the nasopharyngeal epithelium. "Functionally, si-PTBP1 partially reverses the function of linc01513 smart silencer on the proliferation, invasion and migration of nasopharyngeal carcinoma cells." (PMID 35003358, 2021). "In the mechanism, linc01513 may bind and inhibit PTBP1 protein to regulate the malignant progression of nasopharyngeal carcinoma." (PMID 35003358, 2021). "We performed rescue experiments to further verify whether the regulatory effect of linc01513 on nasopharyngeal carcinoma cells is dependent on PTBP1." (PMID 35003358, 2021).
Obesity (2 papers, 2018 to 2023). Accumulation of substantial excess body fat. "However, there is some evidence to indicate how the impairment of PTBP1 may lead to obesity." (PMID 37717070, 2023). "Afterward, we studied the PTBP1 expressions in severe asthmatic and non-asthmatic groups, by considering obesity status; the corresponding probability density function plot, box plot, and violin plot reveal that obesity as internal stress, affects PTBP1 expression level in samples." (PMID 37717070, 2023).
ZIKV infection (2 papers, 2021 to 2026). "Collectively, our findings unveil a novel mechanism underlying that ZIKV infection induces the expression of PTBP1 via the HIF-1α pathway." (PMID 42037413, 2026). "Our previous study has indicated that the expression of PTBP1 increases in astrocytes upon ZIKV infection, yet the precise regulatory mechanisms underlying its role in viral replication remain elusive." (PMID 42037413, 2026). "Among the top selected differentially expressed genes, such as PTBP1, LIF, GHR, PTBP3, EDNRB, and MBP, the mRNA and protein expressions were confirmed to identify the dysregulation of the transcriptome in MPAs upon ZIKV infection." (PMID 33891593, 2021). "Our results showed that mRNA levels of PTBP1, LIF, PTBP3, and GHR were significantly upregulated, while EDNRB and MBP were downregulated upon ZIKV infection at indicated time." (PMID 33891593, 2021). "We found that PTBP1, LIF, GHR, and PTBP3 were upregulated while EDNRB and MBP were downregulated upon ZIKV infection." (PMID 33891593, 2021).
allergic asthma (1 paper, 2024). A asthma with a basis in a pathological type I hypersensitivity reaction. "The genes associated with mucin production (GAL3ST2), leukotriene synthesis (GPX4), Th2-mediated allergic asthma (PTBP1, ZFPM1, SBNO2, and EGFL7), and IgE mediated allergy (PAK2) were also represented in our polygenic prediction models of ICS response." (PMID 38540988, 2024).
astrocytoma (1 paper, 2024). "Interestingly, compared to GBM samples, the analyzed oligodendroglioma samples showed similar but much weaker splicing patterns for the PTBP1 and RBFOX RBPs, whereas the investigated astrocytoma showed patterns that are comparable to normal brain." (PMID 38750024, 2024).
atherosclerosis (1 paper, 2025). A disease characterized by the build-up of fatty material and calcium deposition in the arterial wall resulting in partial or complete occlusion of the arterial lumen. "Once inside the nucleus, NDRG1, through the RNA-binding function of PTBP1, promotes EndMT, leading to decreased stability of atherosclerotic plaques and accelerated progression of atherosclerosis." (PMID 39744686, 2025).
chronic asthma (1 paper, 2023). An asthma that is characterized by the development of persistent airway inflammation and recurrent attacks of breathlessness and wheezing, which vary in severity and frequency. "The chronic asthma phenomena can be a result of cytokines/chemokines, especially TGF-β’s effect on the PTBP1 expression pattern and subsequently, its impact on key signaling molecules." (PMID 37717070, 2023).
Chronic Myeloid Leukemia (1 paper, 2026). "In addition, PTBP2 has been shown to regulate survival and proliferation in Chronic Myeloid Leukemia, making it likely that PTPB2 at least partially compensates for PTBP1 loss in AML cells." (PMID 41214140, 2026).
cognitive decline (1 paper, 2015). "Collectively, we report the association of three RNA biomarkers, COPZ1, EFTUD2 and PTBP1 with clinical features including cognitive decline in early drug-naïve PD patients." (PMID 26566043, 2015).
Cognitive impairment (1 paper, 2018). Abnormal cognition is characterized by deficits in thinking, reasoning, or remembering. "Further analysis showed that relative expression of both EFTUD2 and PTBP1 was significantly downregulated in PD patients with cognitive impairment compared to PD patients with normal cognition." (PMID 29896099, 2018).
colorectal adenocarcinoma (1 paper, 2018). The most common type of colorectal carcinoma. "In two human colorectal adenocarcinoma lines, HT-29 and COLO 205, that are sensitive to necroptosis induced by treatment with TNFα, zVAD-fmk, and cIAP inhibitor BV6, multiple sgRNAs targeting PTBP1 enhance inclusion of the RIPK1 alternative exon." (PMID 29449584, 2018).
congenital heart disease (1 paper, 2023). A heart disease that is present at birth. "In conclusion, as an alternative splicing factor, PTBP1 is essential during ventricular chamber development, and its deficiency can lead to congenital heart disease." (PMID 37002228, 2023).
COVID-19 (1 paper, 2025). A disease caused by infection with severe acute respiratory syndrome coronavirus 2. "We discovered a chimeric RNA that correlated with COVID-19 disease status and appeared to be dependent upon a loss of PTBP1's function as a splicing repressor." (PMID 40110491, 2025). "We then compared chimeric RNAs found from the PTBP1 knockdown and control groups with those found in the COVID-19 patients' whole blood using STAR-Fusion with the same parameters." (PMID 40110491, 2025). "The ODF3B (ciliary microtubule associated protein 1B)–SCO2 (synthesis of cytochrome c oxidase 2) (OS) and TYMP (thymidine phosphorylase)-SCO2 (TS) chimeric isoforms made up the majority of the 14 chimeras found only in the PTBP1 knockdown and COVID-19 samples." (PMID 40110491, 2025). "The RNA binding protein motifs of SFPQ and PTBP1 were found to be the top enriched RBP motifs in COVID-19 patient chimeras and not in GTEx whole blood chimeras." (PMID 40110491, 2025). ",37, 38, 39 Accordingly, PTBP1 knockdown in primary CD34 cells treated with erythropoietin (EPO) resulted in the detection of OS/TS chimeras, which were also shown to have a significant correlation with asymptomatic disease status in COVID-19 patients." (PMID 40110491, 2025). "The lack of detectable virus in the COVID-19 patient's whole blood suggests PTBP1's role in chimeric RNA generation may be downstream of cytokine signal transduction." (PMID 40110491, 2025).
diffuse large B-cell lymphoma (1 paper, 2022). "Additionally, the ACC, CHOL, uveal melanoma, and THYM cases with genetic alterations showed amplification of PTBP1, whereas all diffuse large B-cell lymphoma, KIRP, and PAAD cases with genetic alterations showed mutations in PTBP1." (PMID 36595978, 2022).
endometrial carcinoma (1 paper, 2025). A malignant tumor arising from the epithelium that lines the cavity of the uterine body. "In this study, we found that​​ PTBP1 knockdown notably inhibited both in vitro cell viability and in vivo tumor growth in endometrial cancer (EC) cells." (PMID 41313521, 2025). "Elevated PTBP1 protein levels were also observed in endometrial cancer tissues compared to normal endometrial tissues." (PMID 41313521, 2025). "Our study proposes a molecular mechanism by which PTBP1 promotes endometrial cancer progression by suppressing ferroptosis​​, suggesting that PTBP1 may be a promising therapeutic target for endometrial cancer." (PMID 41313521, 2025). "Transcriptomic sequencing revealed that PTBP1 depletion might impact lipid metabolism and ferroptosis in endometrial cancer cells." (PMID 41313521, 2025).
enterovirus infection (1 paper, 2018). "Aside from acting as an ITAF, PTBP1 is also involved in mediating the RNA template usage switch that occurs during enterovirus infection, after the accumulation of sufficient levels of viral protein." (PMID 30142213, 2018).
esophageal cancer (1 paper, 2024). A primary or metastatic malignant neoplasm involving the esophagus. "N4‐acetylation of lncRNA CTC‐490G23.2 promotes metastasis of esophageal cancer by increasing CD44 isoform‐selective splicing via interaction with PTBP1." (PMID 39640362, 2024).
gastric adenocarcinoma (1 paper, 2023). "To detect the expression of PTBP1 in patients with GC, we used GC tissue microarray (95 cases of survival gastric adenocarcinoma, including 95 cancer sites / 85 paracancer sites) for multiple immunofluorescence staining of PTBP1 and CK (CK staining was used to distinguish epithelial tissues)." (PMID 37670313, 2023). "We performed multiple immunofluorescence experiments on tissue microarray containing 95 cases of survival gastric adenocarcinoma, and found that PTBP1 was highly expressed in tissues of GC patients, and was closely associated with poor prognosis of GC patients." (PMID 37670313, 2023).
gastric tumors (1 paper, 2022). "Intriguingly, bioinformatic analysis from StarBase revealed an apparently positive correlation between SNHG16 and PTBP1 in gastric tumors." (PMID 36447254, 2022). "Similarly, PTBP1 mRNA and protein expressions were obviously increased in gastric tumors compared with normal gastric tissues by qRT-PCR and IHC." (PMID 36447254, 2022). "SNHG16 and PTBP1 were significantly upregulated in gastric tumors and cell lines." (PMID 36447254, 2022). "Totally, fifty-five gastric tumor tissues and their corresponding adjacent normal tissues were collected and the expressions of SNHG16 and PTBP1 were examined by qRT-PCR." (PMID 36447254, 2022).
head and neck squamous cell carcinoma (1 paper, 2024). A squamous cell carcinoma that arises from any of the following anatomic sites: lip and oral cavity, nasal cavity, paranasal sinuses, pharynx, larynx, and salivary glands. "In TCGA, all tumor samples with diverse human cancer types, a significant negative correlation between PTBP1 expression and exon skipping of NDUFV3 was also observed in combined 33 cancer types, and the Head and Neck squamous cell carcinoma (HNSC) serves as a representative example." (PMID 39872664, 2024).
Hepatitis C (1 paper, 2024). "In addition, we found that activation of inflammation-related signalling pathways was associated with hypomethylation of PTBP1 (e.g.,Allograft rejection, Hepatitis C, IL-17 signaling pathway)." (PMID 38918441, 2024).
hepatoblastoma (1 paper, 2023). Hepatoblastoma (HB) is a malignant hepatic tumor and is the most common pediatric liver cancer. "In other pediatric tumors, PTBP2 was expressed at low levels in the metastasis and death cohorts of hepatoblastoma, whereas PTBP1 was highly expressed (GEO: GSE131329)." (PMID 37040518, 2023).
Hydrocephalus (1 paper, 2022). Hydrocephalus is an active distension of the ventricular system of the brain resulting from inadequate passage of CSF from its point of production within the cerebral ventricles to its point of absorption into the systemic circulation. "For instance, knocking out Ptbp1 resulted in differential exon use in Flna and Flnb, which participate in altering neural progenitor cell fate and developing hydrocephalus." (PMID 36478736, 2022).
hyperglycaemia (1 paper, 2020). "Although it is unclear how, it is known that hyperglycaemia promotes the nucleocytoplasmic translocation and recruitment of PTBP1 to preproinsulin mRNA in the cytosol." (PMID 32894308, 2020). "Key to this process is PTBP1, the binding of which to the preproinsulin mRNA 5′-UTR is increased upon transient hyperglycaemia." (PMID 32894308, 2020). "However, exposure of human islets to prolonged hyperglycaemia suppresses PTBP1 expression and insulin biosynthesis, possibly due to the concomitant upregulation of microRNA (miR)-133a, which binds to the 3′-UTR of PTBP1 mRNA." (PMID 32894308, 2020).
intracranial aneurysms (1 paper, 2024). "In a recent study investigating the potential of the PTBP1 gene (cg00999243) to predict intracranial aneurysms, findings showed that long-term exposure to tobacco smoke leads to hypermethylation of its promoter region." (PMID 39415250, 2024).
ischemia (1 paper, 2026). A hypoperfusion of the BLOOD through an organ or tissue caused by a PATHOLOGIC CONSTRICTION or obstruction of its BLOOD VESSELS, or an absence of BLOOD CIRCULATION. "Moreover, shRNA-Ptbp1 treatment mitigated OGD-induced increases in PTBP1 and the astrocyte activation marker GFAP, indicating the crucial role of PTBP1 in astrocyte dysfunction following ischemia." (PMID 41328340, 2026).
lymphoblastic leukemia (1 paper, 2026). "We observed co-immunoprecipitation of PTBP1 and RUNX1 in all the cell lines tested, indicating that the interaction between PTBP1 and RUNX1 is present in both myeloid and lymphoblastic leukemia cells." (PMID 41214140, 2026).
male infertility (1 paper, 2024). The inability of the male to effect fertilization of an ovum after a specified period of unprotected intercourse. "Deletion of PTBP1 in mouse germ cells suppresses spermatogonia cell proliferation, resulting in male infertility." (PMID 39373517, 2024). "Here, we report that deletion of PTBP1 in mouse Sertoli cells disrupts the BTB function, spermatid transport, adhesion, and differentiation, resulting in male infertility." (PMID 39373517, 2024).
metabolic dysfunction-associated steatohepatitis (1 paper, 2024). Metabolic dysfunction-associated steatohepatitis (MASH, formerly known as nonalcoholic steatohepatitis or NASH) is a type of fatty liver disease. "Importantly, PTBP1 expression was significantly increased in the livers of patients with fibrosis and metabolic dysfunction-associated steatohepatitis (MASH, previously known as NASH) compared to normal or steatotic individuals." (PMID 38903178, 2024).
metastasis (1 paper, 2021). The spread or migration of cancer cells from one part of the body (where they first appeared) to another. "For example, polypyrimidine tract-binding protein 1 (PTBP1) directly regulates the splicing of pyruvate kinase isozyme M2 (PKM2) and MEIS2-L, and these two splicing events induce cell proliferation and lymph node metastasis, respectively." (PMID 33842332, 2021).
myeloid leukemia (1 paper, 2025). A clonal proliferation of myeloid cells and their precursors in the bone marrow, peripheral blood, and spleen. "PTBP2 and its paralog, PTBP1, which plays a role in B-cell development, was found to be expressed aberrantly in myeloid leukemia." (PMID 40113750, 2025).
Myeloid Malignancies (1 paper, 2026). "Germline mutations in RUNX1 lacking the C-terminus, which would disrupt the interaction with PTBP1, have been reported in patients with Familial Platelet Disorder with associated Myeloid Malignancies." (PMID 41214140, 2026).
Myocardial fibrosis (1 paper, 2024). "miR-133b binds to the 3′-UTR of PTBP1 and TAGLN2 mRNAs to regulate downstream targets, suggesting that its protective effect on cardiomyocyte apoptosis and myocardial fibrosis may occur through inhibiting PTBP1 and TAGLN2 expression." (PMID 39595980, 2024).
myocardial infarction (1 paper, 2025). Gross necrosis of the myocardium, as a result of interruption of the blood supply to the area, as in coronary thrombosis. "The binding of lncRNA‐SNHG8 and PTBP1, which regulates ALAS2 expression, increases oxidative stress and promotes myocardial infarction." (PMID 40032652, 2025).
oral squamous cell carcinoma (1 paper, 2018). "It has been reported that SRSF3 regulates the expression of PTBP1 and PTBP2 in HEK-293 (human embryonic kidney epithelial cell) and CAL 27 (oral squamous cell carcinoma) cells." (PMID 30279379, 2018).
ovarian adenocarcinoma (1 paper, 2020). An adenocarcinoma that arises from the ovary. "Ovarian adenocarcinoma-amplified lncRNA (OVAAL) binds to polypyrimidine tract-binding protein 1 (PTBP1) and reduces the recruitment of PTBP1 to the internal ribosome entry site of p27 mRNA, thus imparting an inhibitory effect on p27 mRNA translation in cancer cells." (PMID 32429086, 2020).
pituitary adenomas (1 paper, 2022). "Compared with aggressive pituitary adenomas, PTBP1 and eIF5A were highly expressed in primary pituitary adenomas." (PMID 35836612, 2022). "High expression of SLC27A1 and low expression of EIF5A and PTBP1 may be potential indicators to predict the progression of aggressive pituitary adenomas, and patients with high SLC27A1 subtype may be sensitive to TMZ in clinical treatments." (PMID 35836612, 2022). "In pituitary adenomas, the subsequent immunohistochemical results confirmed the differential expression of SLC27A1, PTBP1, and EIF5A genes in aggressive pituitary adenomas and primary pituitary adenomas, and the difference was statistically significant." (PMID 35836612, 2022). "In tumour tissues, mRNA sequencing showed that PTBP1 and EIF5A were significantly overexpressed in primary pituitary adenomas and SLC27A1 was significantly overexpressed in aggressive pituitary adenomas." (PMID 35836612, 2022). "In summary, our study demonstrates that the high expression of SLC27A1 and the low expressions of PTBP1 and EIF5A predict the progression of an aggressive pituitary adenoma." (PMID 35836612, 2022). "Through a comprehensive analysis of the results of histological and cytological experiments, we found that the expression of SLC27A1 was significantly high in aggressive pituitary adenomas and TMZ therapy sensitive cell lines, while the expression of PTBP1 and EIF5A was significantly decreased." (PMID 35836612, 2022). "Therefore, SLC27A1, PTBP1, and EIF5A may be important molecular markers for predicting the recurrence of pituitary adenomas." (PMID 35836612, 2022). "After the data of the two groups were overlapped, it was found that PTBP1 and EIF5A were highly expressed in the primary pituitary adenomas and normal control pituitary tumor cells, and SLC27A1 was highly expressed in aggressive pituitary adenomas and TMZ-treated ATt20 cells." (PMID 35836612, 2022).
retinoblastoma (1 paper, 2025). A malignant tumor that originates in the nuclear layer of the retina. "Post-translational modifications in PTBP1 under splicing conditions with WERI retinoblastoma nuclear extract." (PMID 40465779, 2025). "Post-translational acetyl, phosphate, and methyl modifications in PTBP1 incubated in splicing reaction mixtures containing WERI retinoblastoma nuclear extract." (PMID 40465779, 2025).
Rett syndrome (1 paper, 2020). A severe neurodevelopmental disorder affecting the central nervous system. "We show that cold-induced RNA-binding proteins rescue the neurite outgrowth defects in Rett syndrome using neuronal morphology analysis, and we also reveal that SRSF1 and PTBP1 are required for energy expenditure in adipocytes using metabolic flux analysis." (PMID 32546682, 2020).